SFRP2 (secreted frizzled related protein 2)
Diseases named in the same sentence as SFRP2 in open-access papers (continued):
Sharing a sentence is not in itself a finding about the gene and the disease.
glioma (continued). "As SFRP2 was dramatically decreased in radiotherapy treated glioma patients, we speculated that downregulation of SFRP2 might facilitate Wnt signaling activation in these glioma patients." (PMID 34852024, 2021). "We used the CRISPR/Cas9 system to knock out SFRP2 in glioma cells." (PMID 34852024, 2021). "Furthermore, we found that pharmacological inhibition of Wnt/β-catenin signaling abrogated the effects of SFRP2 knockdown on soft agar colony formation, cancer stemness and radioresistance of glioma cells." (PMID 34852024, 2021). "The influence of SFRP2 knockdown on radiosensitivity of glioma cells was evaluated." (PMID 34852024, 2021). "The expression of SFRP2 in glioma cell lines was evaluated by qRT-PCR." (PMID 34852024, 2021). "The expression of SFRP2 was further analyzed in 662 glioma patients from the TCGA database." (PMID 34852024, 2021). "The influence of SFRP2 overexpression on glioma cells were evaluated." (PMID 34852024, 2021). "In addition, we found that SFRP2 regulated Wnt/β-catenin activation, and pharmacological inhibition of Wnt/β-catenin signaling by XAV-939 abrogated the effects of SFRP2 knockdown on cancer stemness and radioresistance in glioma." (PMID 34852024, 2021). "Taken together, our data indicated that Wnt signaling was activated in radiotherapy treated glioma patients, and this might due to downregulation of SFRP2." (PMID 34852024, 2021). "Similarly, glioma cells that were experimentally designed to overexpress SFRP2 did generate larger xenografts in athymic mice compared to their non-mutated counterparts." (PMID 33140138, 2021). "SFRP2 is downregulated in glioma patients by promoter hypermethylation." (PMID 34852024, 2021). "As SFRP2 was decreased by radiation treatment, we speculated that SFRP2 might affect cancer stemness of glioma cells." (PMID 34852024, 2021). "Correlation between SFRP2 expression and clinicopathological characteristics of glioma patients." (PMID 34852024, 2021). "In addition, SFRP2 knockdown promoted radioresistance of glioma cells and reduced cell apoptosis induced by X-ray irradiation, while overexpression of SFRP2 exhibited opposite effects." (PMID 34852024, 2021). "As SFRP2 was obviously downregulated in radiotherapy treated glioma patients, we speculated that the changing of SFPR2 expression level might correlated with Wnt signaling activation in these patients." (PMID 34852024, 2021). "SFRP2 is frequently downregulated by promoter hypermethylation in glioma patients." (PMID 34852024, 2021). "SFRP2 expression in 166 glioma patients was evaluated by qRT-PCR." (PMID 34852024, 2021). "Moreover, SFRP2 is proved to downregulate in a variety of cancers by promoter hypermethylation, including glioma." (PMID 34852024, 2021). "Our data suggested that SFRP2 acted as a tumor suppressor in glioma." (PMID 34852024, 2021). "The expression of SFRP2 was negatively correlated with advanced tumor stage of glioma patients." (PMID 34852024, 2021). "SFRP2 can act as tumor suppressor in cancers, including glioma." (PMID 34852024, 2021). "Besides, pharmacological inhibition of Wnt/β-catenin signaling by XAV-939 abrogated the effects of SFRP2 knockdown on cancer stemness and radioresistance of glioma cells." (PMID 34852024, 2021). "Our results for the first time demonstrated a role of SFRP2 in radioresistance of glioma cells, and suggested that inhibition of Wnt/β-catenin signaling might be a potential strategy for increasing radiosensitivity of glioma patients." (PMID 34852024, 2021). "Our data for the first time demonstrated a role of SFRP2 in radioresistance of glioma cells, and suggested that inhibition of Wnt/β-catenin signaling might be a potential strategy for increasing radiosensitivity of glioma patients." (PMID 34852024, 2021). "POU3F2 decreased upon SFRP2-overexpression and correlated positively to SOX2 expression in the CCLE glioma cell lines." (PMID 34021259, 2021).
glioma (continued). "Our experimental findings of SFRP2 and SOX2 signaling events represent a scenario whereby SFRP2 counteracts SOX2 function allowing glioma cell progression from a proneural towards a mesenchymal phenotype." (PMID 34021259, 2021). "A series of genes such as EN1, S100A4, ANXA1, PDPN, IGFBP2 and CHI3L1 were upregulated in radiotherapy treated glioma patients, while other genes such as PRLHR, SFRP2, BRINP1, TRIM67, LHX5, KCNIP2 and NSG2 were downregulated." (PMID 34852024, 2021). "The SFRP2 level was dramatically decreased in glioblastoma patients (grade IV, n = 153) compared with patients with grade II (n = 248) or III (n = 261) gliomas." (PMID 34852024, 2021). "Forty‐six glioma samples and one non‐neoplastic brain sample were analyzed by MS‐HRM in terms of SFRP1, SFRP2, RUNX3, CBLN4, INA, MGMT, and RASSF1A promoter methylation." (PMID 32783304, 2020). "The methylation of SFRP1, SFRP2, PPP2R2B, DKK1, SOX17, and DACH1 was analyzed in 64 glioma samples using methylation-specific polymerase chain reaction (MSP)." (PMID 26337424, 2016). "Beside the genes, which were described earlier as possible targets of epigenetic silencing in gliomas (SFRP1, SFRP2, DKK1), the methylation of PPP2R2B, SOX17, and DACH1 was also assessed." (PMID 26337424, 2016). "Our data also indicated that SFRP2 acted as an antagonist but not agonist for Wnt/β-catenin signaling in glioma cells, and these results are supported by other studies, too." (PMID 34852024, 2021). "We found that SFRP2 was significantly downregulated in radiotherapy treated glioma patients compared with non-radiotherapy treated glioma patients." (PMID 34852024, 2021). "In IHC staining, non-radiotherapy treated glioma patients showed increasing number of SFRP2 positive cells compared with that in radiotherapy treated glioma patients." (PMID 34852024, 2021). "However, the potential function of SFRP2 in radioresistance of glioma patients has not been studied before." (PMID 34852024, 2021). "Moreover, SFRP2 regulated Wnt/β-catenin activation in glioma cells, and pharmacological inhibition of Wnt/β-catenin signaling by XAV-939 abolished the effects of SFRP2 knockdown in glioma cells." (PMID 34852024, 2021). "To determine whether the effect of SFRP2 in glioma cells was mediated by Wnt/β-catenin signaling, we used a Wnt/β-catenin pathway inhibitor XAV-939 to restrain Wnt/β-catenin signaling activation in glioma cells." (PMID 34852024, 2021). "To identify novel intermediate regulatory factors between SFRP2 and SOX2 we hypothesized that activity of such genes should increase or decrease upon SFRP2-overexpression but not upon SOX2-overexpression, and correlate with SOX2 expression in the CCLE glioma cell lines." (PMID 34021259, 2021).
lung cancer (13 papers, 2008 to 2024). A malignant neoplasm involving the lung. "Wnt-activating and tumour-promoting roles of SFRP2 have previously been identified in colon and lung cancer, as well as in glioblastoma, and our study suggests a similar role in ovarian cancer." (PMID 38361045, 2024). "Other studies also reported that sFRP2 can activate the canonical Wnt signaling pathway in different cell types and disease models, including lung cancer cells 15, dermal papilla cells 16, intestinal epithelial cells 17, the vertebrate optic disc 18, and cardiac fibroblast cells." (PMID 32071544, 2020). "SFRP2 hypermethylation has also been shown in several cancers including acute myeloblastic leukemia, mesothelioma, bladder cancer, liver cancer, as well as lung cancer." (PMID 28422739, 2017). "SFRP2 has been previously identified as epigenetic target in other tumor entities, such as colon, oesophagus, bladder, stomach, liver and lung cancer." (PMID 18990230, 2008). "However, SFRP2 could also be a tumour-promoting protein and an agonist to the Wnt pathway in lung cancer." (PMID 37999144, 2023). "A study based on three human lung cancer cell lines (95-D, SPCA-1, and A549) showed that the SFRP2 protein level was significantly higher in 95-D cells compared to A549 cells." (PMID 37999144, 2023). "Using an anti-SFRP2 antibody, a clear vessel staining was also observed in tissue sections of angiosarcoma, prostate cancer, HCC, CRC, renal cell carcinoma, lung cancer, ovarian cancer, and pancreatic cancer." (PMID 33140138, 2021). "SFRP2 and WIF1 promoter methylation was previously suggested to play important roles in Wnt signaling in lung cancer." (PMID 28422739, 2017). "Six DMRs located on HOXA9, HOXD3, PCDH17, NID2, NPTX2, and SFRP2 genes exhibiting clinical accuracy over 75% irrespective of lung cancer subtype and cancer progression stages were selected as lung cancer-specific exosome DNA methylation biomarkers." (PMID 39123492, 2024). "Additionally, these authors analysed the effect of knockdown and overexpression of the SFRP2 protein and found that SFRP2 was an agonist of the WNT pathway and promoted the proliferation and invasion of lung cancer." (PMID 37999144, 2023). "Our finding that upregulated miR-128-3p in NSCLC cells simultaneously suppresses multiple negative regulators of β-catenin and TGF-β signalling, including Axin1, SFRP2, WIF1, SMURF2 and PP1c, provides unique insights in understanding the modulation of the β-catenin and TGF-β pathways in lung cancer." (PMID 28627514, 2017).
prostate carcinoma (12 papers, 2010 to 2024). A carcinoma that arises from epithelial cells of the prostate gland. "On performing gene ontology analysis, CpG sites in cluster 2 were found to be related to known genes e.g., RARB, GSTP1, RASSF1, SFRP2, which are implicated in prostate cancer." (PMID 39661598, 2024). "SFRP2 is a potential prognostic and diagnostic biomarker in breast and prostate cancers." (PMID 37887568, 2023). "The promoter of SFRP2 gene, encoding a WNT signaling modulator, is hypermethylated in many cancer types including prostate cancer." (PMID 36552843, 2022). "In this study, we found that overexpression of SFRP2 in the prostate cancer cell line PC3 increases the expression of osteoblast-like genes, when seeded on the most abundant bone extracellular matrix (ECM) structural protein, collagen 1 (COL1)." (PMID 36552843, 2022). "It is known that the SFRP2 promoter is hypermethylated in primary prostate cancer, and, thus, SFRP2 expression is silenced relative to adjacent prostate tissues." (PMID 36552843, 2022). "After prostate cancer cells leave the primary site, demethylation of the SFRP2 promoter likely drives cancer cells towards bone to eventually metastasize." (PMID 36552843, 2022). "MSCs recruited to the regrowing prostate can be used as a vehicle for transporting genetic information with potential therapeutic effects on castrate resistant prostate cancer, for instance by antagonizing Wnt signaling through SFRP2." (PMID 20886110, 2010). "Therefore, SFRP2 promotes an osteoblastic phenotype in early metastasized prostate cancer cells and therewith promotes cell survival, or it additionally induces osteoblastic bone lesion in later stages due to an increase in osteoblastic differentiation." (PMID 36552843, 2022). "Here, we showed SFRP2 overexpression in the prostate cancer cell line PC3 induces an epithelial mesenchymal transition (EMT), increases the attachment, and modifies the transcriptome towards an osteoblast-like phenotype (osteomimicry) in a collagen 1-dependent manner." (PMID 36552843, 2022). "However, further experiments will be needed to demonstrate demethylation of SFRP2 in primary and metastatic cancer tissues and to confirm elevated SFRP2 serum levels to detect the type and location of the early bone metastasis of prostate cancers." (PMID 36552843, 2022). "Moreover, SFRP2 might be a potential molecular candidate to detect bone metastasis in prostate cancer patients before fatal outcomes develop." (PMID 36552843, 2022). "More recently, an assay that evaluates the methylation of GSTP1, SFRP2, IGFBP3, IGFBP7, APC and PTGS2 genes to specifically identify individuals with a severe probability of developing prostate cancer has been proposed." (PMID 37511475, 2023). "In prostate carcinoma, a high frequency of alterations in the promoter methylation status of HIC1, SFRP2, and DAPK1 was detected in patients with prostate carcinomas of high Gleason Score (GS)." (PMID 37388742, 2023). "As our data indicate that SFRP2 causes a molecular and phenotypical switch of PC3 cancer cells towards more osteoblast-like cells, these novel findings may help to monitor the osteotropic activity of metastatic prostate cancer cells in all phases of bone metastasis." (PMID 36552843, 2022). "Interestingly, in the two latter mentioned studies, DNA hypermethylation of SFRP2, SFRP3, and SFRP5 was detected in both cell lines and human prostate cancer tissues." (PMID 29079735, 2017).
angiosarcoma (10 papers, 2014 to 2021). A malignant tumor arising from the endothelial cells of the blood vessels. "Since angiosarcomas have been reported to represent the signaling abnormalities of pathogenic angiogenesis, we speculated that SFRP2 would also be expressed in human angiosarcomas, which we confirmed by immunohistochemistry." (PMID 24489757, 2014). "Specific blocking of SFRP2 with a monoclonal antibody in xenograph angiosarcoma mice models and cell lines demonstrated anti-angiogenic effects and inhibition of the β-catenin pathway." (PMID 34771683, 2021). "Our laboratory previously reported the development of a hSFRP2 mAb that binds to SFRP2 with high affinity, is well tolerated and is efficacious at inhibiting human triple-negative breast cancer and murine angiosarcoma growth in vivo." (PMID 34070758, 2021). "We recently reported the development of a novel humanized antibody to SFRP2 (hSFRP2 mAb) that was efficacious at inhibiting human triple-negative metaplastic breast cancer and murine angiosarcoma tumors in mice." (PMID 34070758, 2021). "Accordingly, we decided that 5 × 106, and 5 × 107 represented the minimum, and maximum doses respectively of targeted microbubbles for molecular imaging of SFRP2 expression in angiosarcoma." (PMID 28333964, 2017). "We further discovered that SFRP2 is a novel stimulator of angiogenesis in vivo and in vitro, and that antagonism of SFRP2 with a mouse monoclonal antibody inhibited triple negative breast carcinoma and angiosarcoma growth in mice." (PMID 28333964, 2017). "Specifically within angiosarcoma, studies have shown that sFRP2 enhances tumorigenesis as inhibitory antibodies directed towards sFRP2 have demonstrated anti-tumor effects." (PMID 27821163, 2016). "SVR angiosarcoma cells were injected into nude mice, and when tumors were established the mice were injected intravenously with the SFRP2 -targeted contrast agent, or a control streptavidin-coated contrast agent." (PMID 24489757, 2014). "We recently reported the generation of a murine monoclonal antibody to SFRP2 that inhibits angiosarcoma allograft and breast cancer xenograft growth in vivo." (PMID 24489757, 2014). "In this study we report the development of a new molecular imaging reagent to non-invasively monitor the progression of angiosarcoma by targeting SFRP2 in the tumor vasculature." (PMID 24489757, 2014). "Secreted frizzled related protein 2 (SFRP2) is a tumor endothelial marker expressed in angiosarcoma." (PMID 24489757, 2014). "We validated localization and overexpression of SFRP2 in tumor endothelium at the protein level as shown by immunohistochemistry in breast, colon, pancreas, renal, prostate, hepatocellular carcinoma, and angiosarcoma." (PMID 28333964, 2017). "SFRP2 acts as a novel stimulator of angiogenesis in vivo and in vitro by stimulating endothelial cell migration, protecting against apoptosis, and is required for and stimulates angiosarcoma tube formation." (PMID 24489757, 2014). "SFRP2 is a tumor endothelial marker with increased expression in tumor vessels compared to normal vessels, and is expressed in a wide variety of human tumors including angiosarcoma." (PMID 24489757, 2014). "Molecular imaging of SFRP2 expression may provide a rapid, non-invasive method to monitor tumor regression during therapy for angiosarcoma, and contributes to our understanding of the biology of SFRP2 during tumor progression." (PMID 24489757, 2014). "This verifies that SFRP2 localizes to vessels within the angiosarcoma." (PMID 24489757, 2014). "Thus, SFRP2 is a novel therapeutic target for angiosarcoma and other tumors." (PMID 24489757, 2014). "Molecular imaging of SFRP2 expression may provide a rapid, non-invasive method to monitor tumor regression during therapy for angiosarcoma and other SFRP2 expressing cancers, and contribute to our understanding of the biology of SFRP2 during tumor development and progression." (PMID 24489757, 2014).
angiosarcoma (continued). "In angiosarcoma (malignant endothelial tumor), another SFRP protein, SFRP2, has been found to be overexpressed." (PMID 34771683, 2021). "Finally, the Wnt signaling mediator, Secreted frizzle-related protein 2 (SFRP2), activates NFAT to promote migration and tube formation in HCAEC and boosts angiogenesis in a mouse model of angiosarcoma." (PMID 31416282, 2019).
renal carcinoma (10 papers, 2012 to 2022). A carcinoma arising from the epithelium of the renal parenchyma or the renal pelvis. "SFRP2 is a tumor suppressor protein that can induce cell apoptosis, and differential methylation of its promoter region has been associated with leukemias and renal cancer." (PMID 36685876, 2022). "In renal cancer, enforced SFRP2 expression facilitates proliferation and in vivo tumor growth of renal cancer cells by activating canonical Wnt signaling." (PMID 34852024, 2021). "SFRP1 and SFRP2 have shown oncogenic potential by increasing cellular proliferation or invasion and promoting in vivo tumor growth in renal cancer." (PMID 34205081, 2021). "Further in vitro, as well as, in vivo oncogenic potential of SFRP2 have been demonstrated in renal cancer." (PMID 30517191, 2018). "sFRP-2 activated the Wnt pathway and promoted renal cancer growth whereas sFRP-3 expression induced the MMP-3 and ANGPT1 genes in renal cancer and thus contributed to the invasive capability of RCC." (PMID 22325146, 2012). "The methylation levels of six Wnt antagonist genes (sFRP-1, sFRP-2, sFRP-4, sFRP-5, Wif-1, and Dkk-3) were significantly higher in renal cancer compared to normal renal tissues." (PMID 22325146, 2012). "Furthermore, in renal cancer, SFRP2 was also shown to have oncogenic potential; SFRP2 promoted both in vitro cellular proliferation and in vivo tumour growth." (PMID 28218291, 2017).